TESC (tescalcin)
Description:
Functions as an integral cofactor in cell pH regulation by controlling plasma membrane-type Na(+)/H(+) exchange activity. Promotes the maturation, transport, cell surface stability and exchange activity of SLC9A1/NHE1 at the plasma membrane. Promotes the induction of hematopoietic stem cell differentiation toward megakaryocytic lineage. Essential for the coupling of ERK cascade activation with the expression of ETS family genes in megakaryocytic differentiation. Also involved in granulocytic differentiation in a ERK-dependent manner. Inhibits the phosphatase activity of calcineurin.
Synonyms: TSC; CHP3; FLJ20607
Tractability: Antibody: UniProt places it where antibodies can reach, with high confidence; its Gene Ontology location is reachable by antibodies, with high confidence. PROTAC: ubiquitination databases record sites on it; its protein half-life has been measured.
Gene: Protein-coding gene on chromosome 12 (117,038,923 to 117,099,479, reverse strand). Ensembl gene ENSG00000088992.
Subcellular location: Nucleus; Cytoplasm; Membrane; Cell membrane; Cell projection, lamellipodium; Cell projection, ruffle membrane
Subcellular location (Human Protein Atlas): Nucleoplasm; Cytosol
Gene Ontology:
Molecular function: calcium ion binding; protein binding; magnesium ion binding; phosphatase inhibitor activity; protein homodimerization activity
Biological process: cellular response to retinoic acid; negative regulation of cell population proliferation; positive regulation of DNA-templated transcription; positive regulation of gene expression; positive regulation of granulocyte differentiation; positive regulation of megakaryocyte differentiation; positive regulation of sodium:proton antiporter activity; protein localization to plasma membrane; protein maturation; protein stabilization; regulation of cell adhesion mediated by integrin; intracellular sodium ion homeostasis; regulation of intracellular pH
Cellular component: cation-transporting ATPase complex; cytoplasm; cytosol; lamellipodium; nucleoplasm; nucleus; plasma membrane; basolateral plasma membrane; ruffle; membrane; ruffle membrane
Genetic constraint (gnomAD): Loss-of-function variants: 19 observed, 25.04 expected, observed/expected ratio (o/e) 0.76, 90% interval 0.53 to 1.11. The upper end of that interval is the gene's LOEUF score, 1.11, which puts it in group 4 of 6, group 1 being the genes least tolerant of losing a copy. Missense variants: 248 observed, 280.73 expected, observed/expected ratio (o/e) 0.88, 90% interval 0.8 to 0.98. Synonymous variants: 109 observed, 105.1 expected, observed/expected ratio (o/e) 1.04, 90% interval 0.89 to 1.22.
Homologues: Orthologues: chimpanzee TESC (99% identical), macaque TESC (99% identical), mouse Tesc (97% identical), pig TESC (97% identical), dog TESC (90% identical), rat Tesc (89% identical), guinea pig TESC (88% identical), tropical clawed frog tesc (66% identical), rat Tescl (61% identical), mouse Tescl (59% identical), rabbit TESC (58% identical), zebrafish tescb (56% identical), and 8 more. Paralogues in human: CHP1 (33% identical), CHP2 (26% identical), PPP3R1 (24% identical), PPP3R2 (23% identical), CIB2 (21% identical), CIB4 (21% identical), CIB1 (20% identical), CIB3 (20% identical).
Diseases named in the same sentence as TESC in open-access papers:
TESC is named in the same sentence as 25 diseases in open-access papers, as found by Europe PMC text mining. Sharing a sentence is not in itself a finding about the gene and the disease. The quoted sentences say what the papers report.
colorectal cancer (8 papers, 2014 to 2022). A primary or metastatic malignant neoplasm that affects the colon or rectum. "Furthermore, TESC has been suggested as a potential diagnostic marker for colorectal cancer because serum TESC levels are elevated in patients with CRC." (PMID 30013043, 2018). "TESC may be a potential oncotarget in colorectal cancer and may have potential clinical value as a diagnostic marker for colorectal cancer screening." (PMID 24811141, 2014). "Thus, TESC is a potential diagnostic marker and oncotarget in colorectal cancer." (PMID 24811141, 2014). "In line with the results obtained in our study, knockdown of TESC led to decreased cell migration as well as invasion of colorectal cancer cells." (PMID 35173149, 2022). "For instance, downregulation of TESC declined the colorectal cancer cell migration and invasion through the suppression of the EMT and MMP signaling pathway." (PMID 35641944, 2022). "TESC was found to be upregulated in both thyroid cancer tissues and cells in this study, which was the same as various cancers, including colorectal cancer, melanoma, renal cell carcinoma and gastric cancer." (PMID 35641944, 2022). "TESC was overexpressed in tissues and sera from patients with colorectal cancer compared with control subjects and depletion of TESC using siRNA inhibited cell proliferation." (PMID 24811141, 2014). "TESC protein was strongly expressed in cancerous lesions of colorectal cancer tissues but slightly in normal mucosal epithelial cells by immunohistochemical analysis (IHC)." (PMID 24811141, 2014). "Therefore, TESC may be a potential diagnostic marker for colorectal cancer." (PMID 24811141, 2014). "Similarly, TESC codes for a member of the calcineurin homologous protein family that has been reported to activate NF-κB and possibly Akt signaling pathways to control the survival and proliferation of colorectal cancer cells." (PMID 26631571, 2015). "As expected, tumor-derived organoids highly expressed in vivo tumor-specific genes, many of which have been widely reported to be closely related to colorectal cancer progression and metastasis, such as PROCR, SCD, BMP4, CEACAM6, TESC, and TGFBI." (PMID 35484598, 2022). "Tescalcin (TESC) regulates cytoplasmic pH via interacting with the NA+/H+ exchanger and promotes the progression of colorectal cancer (CRC) by activating the AKT/NF-κB pathway; upregulation of TESC is also involved in the pathogenesis of CC." (PMID 32708604, 2020). "TESC is overexpressed in colorectal cancer (CRC), but not in normal mucosa and premalignant dysplastic lesions, and its expression contributes to cell proliferation and invasive and metastatic potential." (PMID 30013043, 2018). "To investigate whether TESC affects progression of colorectal cancer, we analyzed proliferative activity in COLO205 and SW620 cells that were transfected with TESC siRNA." (PMID 24811141, 2014). "Tescalcin (TESC) is an EF-hand calcium binding protein that is differentially expressed in several tissues, however it is not reported that the expression and functional roles of TESC in colorectal cancer." (PMID 24811141, 2014). "Here we demonstrated that TESC is overexpressed in colorectal cancer (CRC), but was not expressed in normal mucosa and premalignant dysplastic lesions." (PMID 24811141, 2014). "Silencing of TESC suppressed NF-κB expression in COLO205 or SW620 colorectal cancer cells, but did not affect PTEN expression." (PMID 24811141, 2014). "Thus, TESC may regulate NF-B expression but not NF-κB upstream signaling pathways such as PTEN, and TESC knockdown may suppress the proliferative activity of colorectal cancer cells by inhibiting NF-κB pathway signaling." (PMID 24811141, 2014).
melanoma (2 papers, 2015 to 2022). A malignant, usually aggressive tumor composed of atypical, neoplastic melanocytes. "The results clearly showed that TESC protein expression was remarkably increased in the tissues of gastrointestinal tumors and melanoma (pane 4) compared with that of adjacent normal tissues." (PMID 26169368, 2015).
thyroid cancer (2 papers, 2022). "And the mRNA expressions of TESC in the human thyroid carcinoma cell lines TPC-1, BHT101, 8305C and CAL-62 were also prominently enhanced compared to that in the human normal thyroid cell line Nthy-ori 3–1." (PMID 35641944, 2022).
adenoma (1 paper, 2014). A neoplasm arising from the epithelium. "In contrast, premalignant dysplastic lesions (20 tubular and tubulovillous adenomas with dysplasia) showed slight expression of TESC protein (data not shown)." (PMID 24811141, 2014).
Alzheimer disease (1 paper, 2015). A progressive, neurodegenerative disease characterized by loss of function and death of nerve cells in several areas of the brain leading to loss of cognitive function such as memory and language. "The TESC gene encodes a 24 KDa EF-hand calcium-binding protein and has been proposed as a novel genetic influence on hippocampal size and potential risk factor for cognitive decline and dementia that causes Alzheimer’s disease." (PMID 26169368, 2015).
bladder cancer (1 paper, 2017). "Similarly, the expression of PKP2, a desmosomal adhesions protein has been implicated in glioma and bladder cancer metastasis and high expression of Tescalcin, a gene thought to play a role in cell differentiation and implicated in invasive colorectal cancer." (PMID 29199959, 2017).
brain tumors (1 paper, 2024). "Interestingly, TESC has been reported to play oncogenic roles in several cancers, but information about its function in brain tumors is unclear." (PMID 39796709, 2024).
cholangiocarcinoma (1 paper, 2020). A carcinoma that arises from the intrahepatic biliary tree (intrahepatic cholangiocarcinoma) or from the junction, or adjacent to the junction, of the right and left hepatic ducts (hilar cholangiocarcinoma). "In this study, we observed that high expression of TESC is associated with poor prognosis of patients with cholangiocarcinoma." (PMID 32365487, 2020). "In this study, we observed that not only compared with normal biliary tissues but also with other types of cancer, the expression of TESC dramatically increased in cholangiocarcinoma and was associated with poor prognosis of patients with cholangiocarcinoma." (PMID 32365487, 2020). "To address this shortcoming, we analyzed the transcriptomic datasets of cholangiocarcinoma from The Cancer Genome Atlas (TCGA) and Gene Expression Omnibus (GEO) databases and found that TESC is highly expressed in cholangiocarcinoma." (PMID 32365487, 2020). "TESC expression in different pathological subtypes of cholangiocarcinoma was further examined, and we observed that TESC is highly expressed in ICC." (PMID 32365487, 2020). "Our findings provide novel insight into TESC-mediated oncogenesis and reveal that TESC is a potential biomarker and therapeutic target for cholangiocarcinoma." (PMID 32365487, 2020). "Therefore, our data provide novel insight into TESC-mediated oncogenesis and reveal that TESC is a potential biomarker or serves as a therapeutic target for cholangiocarcinoma." (PMID 32365487, 2020). "However, unlike the expression of TESC, we found that CHP1 is dominantly expressed in normal tissues and that the expression of CHP2 does not differ significantly between cholangiocarcinoma and adjacent non-tumor tissues." (PMID 32365487, 2020).
tumor (10 papers, 2014 to 2026). "Here, we identified tumor-intrinsic tescalcin (TESC) as a previously unrecognized phagocytic checkpoint that contributes to immune evasion and ICB resistance in HCC." (PMID 41926218, 2026). "In particular, TESC was strongly expressed in the cytoplasm of tumor cells from CRC tissues compared with normal colonic mucosa and was also intensely expressed on the luminal side of the CRC glandular structures." (PMID 24811141, 2014). "Immunofluorescence staining showed overexpression of TESC and the phospho-NF-κB protein and their co-localization in the tumor cell cytoplasm and periphery in control xenograft tumors." (PMID 24811141, 2014). "The volume and weight of tumor, and the relative IHC staining index of Ki-67 ki-67 were significantly lower with TESC-RNAi treatment in vivo, which also confirmed that downregulation of TESC repressed cell growth." (PMID 35641944, 2022). "Moreover, existing literature has shown that lncRNA ROR facilitates tumor progression by upregulating tescalcin (TESC) expression." (PMID 35173149, 2022). "Knockdown of TESC via RNA interference suppresses tumor growth." (PMID 32365487, 2020). "PTC tumor and adjacent tissues were obtained, followed by measurement of lncRNA ROR and TESC, ALDH1A1, and TUBB3 expression." (PMID 35173149, 2022). "Consequently, our study revealed that lncRNA ROR promotes the cell malignant behaviors and tumor growth of PTC, which is achieved in part by the TESC/ALDH1A1/TUBB3/PTEN axis." (PMID 35173149, 2022). "As expected, we found that TESC expression was significantly increased in AGS and HT29 tumor cells (lane 4) and not observed in the three negative control cells (lanes 1, 2, and 3)." (PMID 26169368, 2015). "Moreover, because the regulatory role for TESC in tumorigenesis was not indicated, we then explored whether TESC serves as a possible downstream ROR-targeting gene to modulate tumor activity." (PMID 26169368, 2015).
cancer (6 papers, 2018 to 2025). A tumor composed of atypical neoplastic, often pleomorphic cells that invade other tissues. "Although TESC expression has also been reported in various types of cancer and potentiates cell proliferation and tumorigenicity, the mechanism behind TESC-mediated oncogenesis is unclear." (PMID 32365487, 2020). "In contrast, TESC overexpression in H460 cells intensified the self-renewal capacity of the cancer cells." (PMID 30013043, 2018). "When cells were exposed to a single dose of γ-radiation (6 Gy), the upregulation of TESC expression conferred resistance to cancer cells and vice versa." (PMID 30013043, 2018). "Recent studies have shown that TESC is involved in the progression of cancer." (PMID 30013043, 2018). "Tescalcin (TESC; also known as calcineurin B homologous protein 3, CHP3) has recently reported as a regulator of cancer progression." (PMID 30013043, 2018).
TESC also shares sentences with these, for which no sentence is quoted: cervical cancer (1 paper); co-infection (1); cognitive decline (1); colon cancer (1); COVID-19 (1); dementia (1); epilepsy (1); gastric cancer (1); gastrointestinal tumors (1); glioma (1); hepatocellular carcinoma (1); infection (1); lung carcinoma (1); pituitary adenoma (1); renal cell carcinoma (1).